CAV1 (caveolin 1)
Diseases named in the same sentence as CAV1 in open-access papers (continued):
Sharing a sentence is not in itself a finding about the gene and the disease.
tumor (continued). "In addition, it must be determined whether correlations exist between Cav-1 expression and tumor stromal and cancer cells, and the mechanisms understood." (PMID 25202343, 2014). "In addition, Y6 and Y14 on Cav1 also exhibited increased phosphorylation, which was of interest, given the close proximity of the Met and Cav1 genes on mouse chromosome 6 and coamplification of these two genes in particular tumour types." (PMID 25200860, 2014). "It was reported that CAV1 present in immune cells may be involved in regulation of the cell signaling and inflammatory response as well as the Jak-Stat signaling pathway and tumour-induced immunosuppression." (PMID 24741625, 2014). "Our results demonstrate that CAV1 could function as a potent tumor suppressor in ARMS tumors." (PMID 25313138, 2014). "Finally, surrounding cancer cells may downregulate Cav-1 in adjacent NFs via oxidative stress to the tumor microenvironment." (PMID 25202343, 2014). "Of note, we were unable to assess whether the loss of Cav-1 could lead to a regression of tumor growth in vivo, because the injected shCav-1 cells had lost the silencing effects yielding tumor masses largely positive for Cav-1 (not shown)." (PMID 24427291, 2014). "In addition, the CAV1-overexpression HepG2 cells has high mRNA level of Twist, a transcription factor highly expressed and crucial in promotion of EMT and consequently tumor cell invasion as well, while the CAV1-knockdown MHCC97-H cells resulted in a decrease in Twist mRNA level." (PMID 25180681, 2014). "In addition, Cav1 depletion can block the association between Src kinases and ß1 integrin, resulting in both the loss of focal adhesion domains that mediate the interaction between the ECM and cytoskeletal proteins and increased tumour migration." (PMID 23521716, 2013). "Additionally, increased expression of transcripts for heat shock proteins, peptidases, ribosomal proteins, ubiquitins, proteins that provide interaction between the cell and the ECM (caveolin-1, integrin-beta-1), tumor suppressors, and epigenetic modifiers were also characteristic of ECb." (PMID 23423481, 2013). "Stratifying patients into four subgroups according to the expression of tumour Cav-1 and pERK-1/2 revealed that tumours lacking expression of both Cav-1 and pERK-1/2 (C-/E- n = 64) were associated with a good prognosis, i.e. DFS of 6.75 yrs and an 80% probability of remaining disease-free at 5 yrs." (PMID 24119769, 2013). "Finally, Cav1 expression can mediate chemo- and radioresistance of tumour cells." (PMID 23521716, 2013). "Higher Cav1 expression in advanced tumours is exploited by the recently developed nanoparticle albumin-bound (nab) technology, which promises to have broad utility in cancer therapy and proposes a mechanism to deliver nab-driven chemotherapy that exploits the cargo properties of Cav1." (PMID 23521716, 2013). "To date, the discordant role of stromal Cav1 on tumour progression and metastasis appears to be poorly understood although several mechanisms have been proposed by different authors to explain its critical function as a regulator of tumour-surrounding tissue remodelling and desmoplastic processes." (PMID 23521716, 2013). "Furthermore, we investigated the prognostic value of Cav-1 expression in tumor cells and CAFs." (PMID 23527097, 2013). "Interestingly, we recently found that overexpression of caveolin-1 decreased tumor invasion and metastasis (unpublished data), supporting the hypothesis that caveolin-1 suppresses tumorigenesis." (PMID 22894556, 2012). "Moreover, depending on the specific model, endothelial caveolin-1 may either promote or suppress tumor-induced angiogenesis." (PMID 26605130, 2012). "In addition, caveolin-1 expression inversely correlates with the tumor size, alpha fetal protein level, vascular invasion, tumor number and pathological TNM (pTNM) staging, which implied that the expression of caveolin-1 gradually decreased with HCC progression." (PMID 22894556, 2012).
tumor (continued). "In lung SCC, cav-1 overexpression may be correlated with tumor extension." (PMID 22200856, 2012). "Thus specific delivery of Cav-1 mimetic peptides to tumor blood vessels of cancer patients could potentially be exploited in antitumor therapy." (PMID 26605130, 2012). "Therefore, Cav-1 levels were higher in claudin-low tumor cells than epithelial tumor cells." (PMID 22356861, 2012). "This evidence indicates that cav-1 may act as a tumor suppressor." (PMID 22200856, 2012). "Applying multivariable Cox regression analysis a high CAV1 protein expression level in the tumor cell cytoplasm could be identified as an independent poor prognostic marker of both overall (p = 0.02) and tumor specific survival (p = 0.03) in clear cell RCC patients." (PMID 22152020, 2011). "Furthermore, high CAV1 protein expression level in the tumor cell cytoplasm could be identified as an independent poor prognostic marker." (PMID 22152020, 2011). "Therefore, the possible loss of cavins in tumor cells opens a new exciting window to explore caveolar and non-caveolar roles of CAV1." (PMID 21471610, 2011). "Wehave independently shown that many of these same biological processes areactivated in Cav-1 (-/-) stromal cells, consistent with the idea that Cav-1(-/-) stromal cells are a valid model for exploring the tumor-promoting effectsof an activated tumor stromal micro-environment." (PMID 20442453, 2010). "Thus, re-expression of Cav-1 at advanced stages of cancer may provide a survival mechanism for tumor cells, and targeting Cav-1 may represent a new stratagem for cancer treatment." (PMID 20700465, 2010). "Loss of the putative tumor suppressor, Cav-1, is believed to be one of the causes for development of several types of cancers, but evidence also show that overexpression or re-expression of Cav-1 in advanced stages of the disease may contribute to tumor progression." (PMID 20700465, 2010). "Finally, in 62 of 95 (65.3%) HCC samples, tumor cells stained positively for Cav-1." (PMID 19239691, 2009). "The selective and/or preferential expression of caveolin-1 on exosomes from tumor patients may thus represent an important marker of malignant progression and deserves further investigation about its possible application as a screening method in tumor patients." (PMID 19381331, 2009). "However, simply restoring Cav-1 expression could indeed suppress tumour growth and reduce distant metastasis in vivo." (PMID 19002186, 2008). "However, the composite covariate of ‘caveolin-1 and activated AKT’ correlated with tumour size, grade and the presence of vascular invasion in an independent manner and to a statistically greater extent than when either variable, caveolin-1 or pAKT was analysed alone." (PMID 18283322, 2008). "Hence, a tumour-suppressive function of Caveolin-1 has been suggested." (PMID 17915016, 2007). "However in other cell types caveolin-1 can act as a tumour suppressor, and cholesterol depletion has been shown to decrease caveolin-1 levels, so this treatment might have deleterious effects in these types of cancer and would have to be used specifically." (PMID 18949068, 2007). "The ability of caveolin-1 to negatively regulate growth factor signalling pathways and cell cycle progression, and its identification as a candidate tumour suppressor, might suggest the possibility of cancer treatments based on caveolin-1 or its scaffolding domain." (PMID 18949068, 2007). "However, caveolin-1 has also been found to be down-regulated in tumours themselves, and several independent studies have shown that the re-expression of caveolin-1 in transformed cells inhibits features of the transformed phenotype, such as anchorage-independent growth." (PMID 18949068, 2007).
tumor (continued). "However, much of the current literature that lends support for caveolin-1 serving as a tumour suppressor protein has been generated by the use of in vitro and ex vivo overexpression systems for caveolin-1 that are assumed to mimic the activity of endogenously expressed caveolin." (PMID 14612902, 2003). "Thus, the role of caveolin-1 in tumour remains controversial." (PMID 12402154, 2002). "Caveolin-1 (Cav-1) is a focal adhesion protein co-localised with β-integrin and FAK and is crucial in signal transduction, tumour invasion, matrix remodelling, and matrix turnover." (PMID 40045379, 2025). "In various tumor cells (e.g., HCC and GC), Cav-1 often inhibits autophagy, promoting malignant progression and correlating with poor prognosis." (PMID 41030451, 2025). "Cav-1 interacts with IGF1R and IR, underscoring its role in metabolic alterations that support tumor growth and progression." (PMID 40243482, 2025). "Network visualization highlighted key gene hubs involved in these processes, including FBLN1, CAV1, FGFR4, and ITGB1, suggesting a possible role for TNBC epithelial cells in modulating the tumor immune microenvironment." (PMID 41595458, 2025). "In our study, Na-OHB induces ferroptosis in tumor cells by downregulating the genes regulated by CAV1/AMPK/NRF2 and affecting the interaction between CAV1 and SLC7A11." (PMID 40180904, 2025). "Core genes with a higher DC (> 8), EC (> 0.06), LAC (> 2.0), BC(> 200), and NC(> 0.3) in the enriched modules were also expressed differentially in TCGA‐CHOL data (36 tumor samples and 9 adjacent cancer samples), including FGF2, IGF1, CAV1, SPON1, and ADAMTS4." (PMID 40304434, 2025). "VEGF, TGF-β, CXCR4, Cav-1, Wnt7a, EGFR and EPHA2 enhance vascular formation and influence tumor microenvironment dynamics." (PMID 40486870, 2025). "Utilizing mouse tumor models, we conducted an in-depth evaluation of the ferroptosis status and the expression changes of CAV1 and SLC7A11 at the single-cell level within tumor tissues." (PMID 40180904, 2025). "Correlation analysis of CAV1 molecules and SLC7A11 showed a significant positive correlation between them, with correlation coefficients of 0.69, 0.61, and 0.88 in the three tumor models, respectively." (PMID 40180904, 2025). "This may be related to physical effects such as shear stress, since the role of CAV1 in response to fluid shear stress has previously been described in endothelial cells and an inhibitory effect of this factor on shear stress-induced anoikis was demonstrated in circulating tumor cells." (PMID 38528578, 2024). "In the methods section CAV1 gene expression in TNBC was evaluated using in silico analysis, followed by the immunohistochemical staining of tumor cytoplasm (cCAV1) and stromal cells (sCAV1) in 58 early-stage TNBC patients." (PMID 39596307, 2024). "Cav1 and MCT4 are known metabolic coupling markers in tumor-fibroblast interactions, and fibroblasts in the tumor microenvironment undergo loss of Cav1 and gain of MCT4." (PMID 38361760, 2024). "The BCL2L1, CAV1, KDELR3 and YWHAZ expression levels were upregulated in the tumour tissues and downregulated in the healthy pancreatic tissues." (PMID 38303549, 2024). "The heatmap demonstrated SERPINE1 was up-regulated in tumor tissues, while the rest four genes (ZFP36, DUSP1, CAV1, and AKAP12) were down-regulated as compared to the normal group." (PMID 39165353, 2024). "The protein levels of three SCLC tumor markers, namely, NSE, CAV1, and MYCL1, were elevated in drug-resistant SCLC cells." (PMID 39594767, 2024). "Eight distinct CAF markers (αSMA, collagen-1, caveolin-1, CD140β, FAP, integrin α11, FSP-1 and CD90) were optimized during this study and validated on five HNSCC tumor samples." (PMID 38803925, 2024). "Decreased Lef1 expression/Re-sensitized tumor cells to docetaxel/Downregulated ABCG2, Vim and Cav1 expression." (PMID 39712006, 2024).
tumor (continued). "Based on the previous studies, Cav1, MCT4, acid lactic, TGFβ, and IL-6 are crucial hallmarks of cancer, involving tumor progression and therapy resistance via promoting metabolic symbiosis." (PMID 38361760, 2024). "Caveolin-1 and mitochondrial SOD2 (MnSOD) function as tumor suppressors in the stromal microenvironment." (PMID 37469162, 2024). "Conversely, CAV1 upregulation induces the accumulation of free Fe2+ in HNSCC cells, which accelerates tumor growth." (PMID 38313306, 2024). "Equal numbers of WT and Cav-1 KO 4T1 cells were injected into the mammary fat pads of female BALB/c mice, and tumor growth was observed over time." (PMID 39244591, 2024). "Wei’s research showed that the expression of CAV1 was significantly reduced in NSCLC, and overexpression of CAV1 can reduce cell migration by affecting the phosphorylation of STAT3, exerting a tumor suppressive effect." (PMID 39165641, 2024). "Even though most biomarkers have pro-tumor effects, a few exert anti-tumor actions; cluster of differentiation 146 (CD146) and caveolin-1 are examples of this type of biomarkers." (PMID 37168385, 2023). "We found that the expression of pY14-caveolin-1 and SPARC protein was highly overlapped in tumor tissues treated with H2O2." (PMID 37528424, 2023). "The enhancement of tumor selectivity with HSA has been reported, which is accompanied by the expression level of receptor and extracellular proteins such as caveolin-1, sialoglycoprotein, and secreted protein acidic and rich in cysteine." (PMID 38203730, 2023). "Analysis and group comparison indicated that the mRNA expression levels of CAV1 and CAV2 genes were significantly higher in tumor tissues compared with those in normal tissues." (PMID 36830672, 2023). "Pericytes play a crucial role in tumor neovascularization; consistently, we observed a strong angiogenic signature (such as for ANGPT2, CAV1, PDGFA, THY1, EGFL6, and GMFG) in pericytes." (PMID 37853464, 2023). "Based above, the relationship between the mRNA levels of CAV1/2 and CAVIN1/2/3 and the tumor stage in LUAD and LUSC were performed using UALCAN." (PMID 37497407, 2023). "CAV1 and CAV2 regulate processes, including tumor growth, cell migration and metastasis, angiogenesis, and drug resistance." (PMID 36830672, 2023). "CAV1 can negatively regulate transforming growth factor-beta (TGF-β) signaling; however, the activation of TGF-β signaling in tumor stromal cells appears to be necessary to induce mitophagy." (PMID 38067169, 2023). "We performed data analysis between the expression levels of CAV1 and CAV2 with the location of the primary tumor and patients’ HPV status." (PMID 36830672, 2023). "Next, we will investigate the structure and function of vessels under conditions of blocking or upregulating caveolin-1, and the corresponding SPARC expression, which would shed light on the role of the caveolin-SPARC pathway in tumor angiogenesis scenario." (PMID 37528424, 2023). "Other interesting issues are the expression on plasmatic exosomes from tumor patients of acknowledged tumor markers (e.g., PSA and CEA) and a series of surrogate tumor markers (e.g., Cav-1, HSP60, and carbonic anhydrase, such as CA IX)." (PMID 37296842, 2023). "CAV1 and ICAM1 upregulation under oxidative stress is also involved in tumor proliferation and migration, as well as chronic lung inflammation." (PMID 37131205, 2023). "Among the FRGs that we have identified in the signature, CAV1 plays a crucial role in the efficient deposition of ECM by fibroblast-derived exosomes, ultimately promoting tumor invasion." (PMID 37711170, 2023). "Therefore, CAV1 displays a dual role in cancer, not only according to the stage of tumor progression but also depending on the presence or absence of specific proteins, like E-cad, which determine whether CAV1 will function as a tumor suppressor or tumor promoter." (PMID 38069269, 2023).
tumor (continued). "In this study, our results showed that down-regulation of COL1A1 increased the expression of E-cadherin and Cav-1 in tumor cells and reduced the expression of α-SMA and FAP, thus improving the tumor microenvironment." (PMID 38045487, 2023). "Recently, some studies believe that CAV1 and CAV2 were expressed low as tumor suppressors in primary BC and cell lines." (PMID 36147736, 2022). "Enzyme-linked immunoassay (ELISA) is used for more specific capturing of tumor-derived exosomes by applying specific antibodies against tumor markers such as Glypican-1 (GPC-1), Caveolin-1 (CAV1), or heat shock protein 90 (HSP90)." (PMID 35033106, 2022). "Specifically, tumor transformation triggered by tumorigenic H-RAS12V in NIH3T3 cells inhibits intracellular basal calcium (Ca2+) levels, Ca2+ influx, and caveolin-1 expression." (PMID 35064107, 2022). "The lower TDM1 accumulation in CAV1-high xenografts, when compared with CAV1-low tumors, prompted us to interrogate if in vivo genetic depletion of CAV1 would boost ADC-tumor binding." (PMID 35534471, 2022). "Furthermore, significantly higher SRC expression levels (together with higher CAV1 phosphorylation levels) were present in the malignant epithelial cells of advanced PCa tumors of higher Gleason grades, whereas immunoreactivities of both proteins were declined within the more reactive tumor stroma." (PMID 35155239, 2022). "Finally, it has been hypothesized that caveolin-1 is a tumor suppressor." (PMID 35064107, 2022). "Caveolin-1 (CAV1) is a membrane protein that has been attributed a dual role in cancer, acting at early stages as a tumor suppressor and in later stages of the disease as a promoter of metastasis." (PMID 35740528, 2022). "The results demonstrate that the expression of EGFR, IGF1, PTGS2, FGF1, CAV1, and PLCB1 were significantly different (p < 0.01) in PABC tissues as compared to non-tumor tissues, with a similar pattern to that observed in the microarray analysis." (PMID 36035177, 2022). "The Caveolin-1(Cav1) and Superoxide Dismutase 1(SOD1) were supposed to as potential tumor suppressor and oncogene respectively." (PMID 36263135, 2022). "Among these biomarkers, Caveolin-1 and GATA-binding protein 3 (GATA-3) were identified as promising markers of tumor aggressiveness." (PMID 36299636, 2022). "To further explore the effect of anti-GD2 mAb plus MβCD on tumor immunity, we detected the protein expression of CD8A, caveolin-1, CXCL9, and CXCL10 by IHC staining." (PMID 36284313, 2022). "Whether Cav1 is an oncogene or a tumor suppressor is debated; however, the answer may be related not only to the levels expressed but also to its function, localization (tumor or stromal cells), type and stage of cancer, or physical forces within the environment of the tumor." (PMID 34207120, 2021). "The results confirmed DLC1, Caveolin-1 and PLCD1 protein levels were lower in tumor tissue compared to normal adjacent lung." (PMID 34727930, 2021). "In conclusion, celastrol effectively attenuated lipid accumulation through inhibiting the interaction of CAV-1 and LOX-1, and then blocked Wnt/β-catenin signaling pathway to impair stem-like properties, thereby suppressed tumor growth of ccRCC." (PMID 33935779, 2021). "Cav-1 and Cav-2 were reported to be regulated by FGFR4 and CDH2 and, also, correlated with tumor progression, invasion and metastasis." (PMID 33809909, 2021). "Furthermore, it has been reported that tumor-derived exosomes may carry different factors involved in the activation of EMT program including TGFβ, caveolin-1, HIF1α, vimentin and β-catenin thus improving the migration ability of cells inside a tumor and contributing to stromal remodelling." (PMID 36046089, 2021). "Several studies have indicated CAV1 is overexpressed in HNSCC and mediates tumor migration and invasion." (PMID 33712015, 2021).